EGFR (epidermal growth factor receptor)
Diseases named in the same sentence as EGFR in open-access papers (continued):
Sharing a sentence is not in itself a finding about the gene and the disease.
cancer (continued). "Since minimal/no growth inhibition effect was observed in EGFR, KRAS-mutated cancer cells in vitro, to confirm the specific inhibiting activity against these oncogenic driver genes, we generated each EGFR and KRAS overexpressed NIH3T3 cells and gilteritinib was treated in vivo." (PMID 33627640, 2021). "Also, YB-1 has been implicated in promoting cancer proliferation via activating EGFR signaling in an exogenous EGF-independent manner." (PMID 34696665, 2021). "Previous studies have shown that lung carcinogenesis is attributed to the gain-functional mutation of several cancer-associated genes, including the epidermal growth factor receptor (EGFR), Kirsten rat sarcoma viral oncogene homolog (KRAS), and v-raf murine sarcoma viral oncogene homolog B1 (BRAF)." (PMID 34422661, 2021). "Uncontrolled EGFR signaling is associated with numerous diseases, including cancer." (PMID 33996800, 2021). "In addition, we compared the analytical sensitivity of the Oncomine Pan-Cancer Cell-Free assay (Thermo Fisher Scientific, Waltham, MA, USA) to that of the Cobas EGFR Mutation Test v2 (Roche Molecular Systems, Pleasanton, CA, USA)." (PMID 34199654, 2021). "Additionally, EVs carrying (mutated) EGFR/HER2 were established as potential biomarkers in liquid biopsies from cancer patients for disease diagnosis or the prediction of therapeutic response." (PMID 33207034, 2021). "However, two distinguishable mechanisms exist between these cancers: either a kinase-activating mutation in EGFR (EGFR-mutant) or an overexpression of the EGFR protein (wt-EGFR)." (PMID 34069119, 2021). "In addition to genetic mutation of EGFR, genetic mutation–independent EGFR activation also contributes to cancer." (PMID 33705793, 2021). "Cancer cells with the L858R mutations and exon 19 deletion may respond to the constitutive activation of the EGFR, which provides strong growth and survival signaling." (PMID 33562150, 2021). "The mutational load in cancer-related genes between naïve and primed appears to be largely similar, if not higher in primed hPSC, where additional point mutations were identified in the cancer-related genes EGFR, PATZ1, and CDK12." (PMID 34831467, 2021). "Aberrant activation of EGFR caused by various alterations such as copy number amplification, mutations, and protein overexpression has been reported in the majority of human cancers, including bladder, breast, colon, head and neck, kidney, liver, lung, ovary, pancreas, prostate, and stomach cancers." (PMID 34207383, 2021). "Cancer drugs significantly associated with EGFR and/or PI3K pathway activity." (PMID 34178665, 2021). "We discovered that several of the miRs might act as a network regulating essential (CRC) cancer-associated pathways, e.g., the EGFR, MAPK, Ras, or the mTOR signaling pathway, amongst others." (PMID 34885060, 2021). "Autocrine/paracrine production of epidermal growth factor receptor (EGFR) ligands, like epiregulin, amphiregulin, and heparin-binding EGF-like growth factor (HB-EGF), and the overexpression of EGFR, are two of the mechanisms most frequently implicated in cancer development and progression." (PMID 34360915, 2021). "Although this cancer is linked to genetic instability, the DNA mutations targeted for adenocarcinoma therapy, including EGFR mutations and echinoderm microtubule-associated protein-like 4 (EML4)-anaplastic lymphoma kinase (ALK) translocations, are essentially absent in LSCC." (PMID 33799513, 2021). "EGFR mutations are more commonly identified in the ctDNA analysis of cases with distant metastasis including liver or bone compared to cases with M1a classification where the cancer is limited to the lung or pleura only." (PMID 34574036, 2021). "As in other types of cancer, specific mutations may increase sensitivity or result in resistance to anti-EGFR therapy." (PMID 33235314, 2021). "Since EGFR is a potent oncogene, EGFR dysregulation will cause several forms of cancer." (PMID 34646755, 2021).
cancer (continued). "The uncontrolled EGFR pathway induces aberrant signaling linked with many airway illnesses, including extreme airway proliferation, hypersecretion, mucus overproduction, and advanced distal lung fibrosis and cancer." (PMID 34976811, 2021). "EGFR is abnormally activated through various mechanisms, such as receptor overexpression, mutation, ligand-dependent receptor dimerization, and ligand-independent activation, and is associated with the occurrence of various human cancers." (PMID 33777163, 2021). "Although the MACC1-induced proliferation of CRC cells can now be linked to enhanced TfR and EGFR recycling, more cancer-related RTKs and respective downstream signaling pathways may be affected by this mechanism and should be the focus of future studies." (PMID 33469705, 2021). "The underlying mechanism behind EGFR-positive cancers, whether it be mutations, gene amplification, or overexpression, has a significant impact on the efficacy of anti-EGFR therapies and resistance patterns." (PMID 34069119, 2021). "EGFR is overexpressed in ~20% of breast and ~80% of CRCs, and activating mutations of Ras are one of the most common cancer-associated genetic alterations." (PMID 34096503, 2021). "In addition, the results of the in vitro evaluation of the anticancer activity of afatinib against a series of cancer cell lines expressing EGFR mutations revealed superior activity compared to the first-generation EGFR inhibitor, erlotinib." (PMID 34771085, 2021). "Since EGFR-driven signaling is related to unregulated cell growth and division through several molecular pathways, EGFR gene mutations and amplifications have been considered targetable alterations in a variety of cancers." (PMID 33451055, 2021). "However, higher inhibitory activities were observed in HCC827 (EGFR del19), PC9 (EGFR del19), and NCI-H1975 (EGFR L858R/T790M) cancer cell lines harboring an EGFR mutation (IC50 = 3.3–4.1 nM)." (PMID 34771085, 2021). "Loss of MIG6 could account for the elevation of EGFR expression and signaling in several cancer types, including HCC." (PMID 33806040, 2021). "By combining the presence of resistance co-mutations in other cancer-related genes with the allelic frequency of the EGFR mutation, we hypothesized that we would more accurately capture the driver status of EGFR and predict treatment response." (PMID 33869038, 2021). "Thus, this study demonstrates the underlined anti-cancer mechanism of SG by interfering with EGFR dimerization." (PMID 33946151, 2021). "Most anti-EGFR therapeutics are effective in cancers that have activated mutations in EGFR." (PMID 33801977, 2021). "Therefore, agents for targeting PTEN-deficient cancers or inducing synergistic effects with EGFR-TK inhibitors have been proposed." (PMID 34681198, 2021). "In addition, we subdivided the cancer samples into two groups: (i) tumors that had known clinically relevant mutations in EGFR signaling genes: EGFR, KRAS, NRAS, and BRAF, and (ii) “wild type” tumors that did not have these mutations." (PMID 33748471, 2021). "However, the Pan-Cancer Cell-Free assay appeared to be slightly more sensitive than the Cobas EGFR assay, with 50% and 25% detection of the variants, respectively." (PMID 34199654, 2021). "However, the patient (patient ID 9) likely had two metachronous primary cancers because one of the two target lesions that progressed was found to not harbor an EGFR mutation (the target lesion harboring the EGFR mutation remained stable on treatment)." (PMID 34568058, 2021). "ERB1/EGFR was the first tyrosine kinase receptor to be discovered and linked to cancer." (PMID 33918836, 2021).
cancer (continued). "EGFR amplification which commonly occurs due to mutation also occurs in breast, lung, ovarian, and prostate cancers." (PMID 34867402, 2021). "EGFR is commonly known to be implicated in cell proliferation, survival, migration, and differentiation and, hence, its activation plays an important role in cancer biology." (PMID 34201116, 2021). "The overexpression, amplification and mutation activation of EGFR can induce cancer." (PMID 33633793, 2021). "GPCR and EGFR are two pivotal families of drug targets, given that GPCR-induced transactivation of EGFR has been linked to cancer development (Köse, 2017), through the activation of MAPK signaling, stimulation of cell migration, and regulation of cell-cycle progression." (PMID 34658851, 2021). "Consequently, we identified an EGFR-associated feedback loop that promotes PASC progression from ductal cells to cancer cells." (PMID 34326696, 2021). "The upregulation of EGFR levels is associated with cell cycle dysregulation and cancer development." (PMID 34577547, 2021). "Most EGFR mutations are either short deletions in exon 19 or an L858R substitution in exon 20, and these EGFR-activating mutations subsequently stimulate EGFR downstream signaling pathways, which leads to the proliferation and invasion of cancer cells." (PMID 34068421, 2021). "We detected seven new EGFR genetic variants in 168 cancer patients and 114 controls." (PMID 33874989, 2021). "In general, molecular signaling begins by receptor binding, and EGFR is a famous receptor in cancer formation where its mutation may lead to tumorigenesis." (PMID 34209829, 2021). "This last finding underlines the importance of UBTD1 in EGFR-driven cell proliferation and may be further investigated in an EGFR hyper-activated state such as cancer." (PMID 33884955, 2021). "Gene amplification and activating point mutations of EGFR are highly prevalent in cancer." (PMID 34096503, 2021). "EGFR activation therapy works well in clinical practice but has not shown progress in the past few decades, partly because its long-term use may cause cancer." (PMID 34539797, 2021). "Additionally, previous studies have demonstrated an association between serum cholesterol and survival in patients with resectable NSCLC (as well as other forms of cancer) and an association between membrane cholesterol content and EGFR signaling activity." (PMID 34822397, 2021). "Interestingly, the majority of these EGFR‐associated cancers are located at sites where C. albicans commonly infects, with reports providing contrasting evidence both for and against elevated incidences of candidiasis in these patients." (PMID 32880925, 2021). "This could be relevant as high TMB is known to be associated with poor prognosis in patients whose cancer harbors an EGFR mutation." (PMID 33869038, 2021). "EGFR is considered an important therapeutic target for multiple cancers, but the mechanism underlying its dysregulation remains unclear." (PMID 33909822, 2021). "CMS2 cancers, which rarely exist in patients with MA/MC and is characterized by the activation of the EGFR pathway may be associated with enhanced sensitivity to cetuximab." (PMID 33939281, 2021). "In addition, resistant subclones containing an additional EGFR mutation has been observed in cancer patients bearing erlotinib-sensitive EGFR mutations." (PMID 34322025, 2021). "By disturbing EGFR signaling, mutations of EGFR may lead to progression of cancer or the emergence of resistance to EGFR-targeted drugs." (PMID 34112110, 2021). "However, activation of EGFR signaling is critical in cell proliferation, apoptosis, angiogenesis and other processes associated with cancer progression." (PMID 34879870, 2021).
cancer (continued). "Inappropriate activation of EGFR through gene amplification, mutation, abnormal protein overexpression, ligand overproduction, and dysregulated intracellular trafficking plays an important role in cancers." (PMID 33641663, 2021). "Mutations in the components of the EGFR pathway are known to be associated with human cancers." (PMID 34604068, 2021). "Cancer genome sequencing efforts reveal that in addition to mutations in growth-promoting signaling pathways such as in EGFR and KRAS, chromatin-modifying enzymes and epigenetic regulators such as KMT2D, ARID1A, and TET2 are also frequent targets of genetic alterations." (PMID 34236315, 2021). "The indispensable genes are directly associated with cancers, especially EGFR, MAX, MNT, SMAD3." (PMID 33968733, 2021). "The overexpression of the EGFR is associated with different types of cancers." (PMID 34771085, 2021). "It was worth noting that BDNF and its similar genes were notably associated with EGFR tyrosine kinase inhibitor resistance, which might provide evidence for their potential role in cancer-targeted treatment." (PMID 34777634, 2021). "Upregulating HER3 in cancer cells is also associated with resistant to EGFR TKIs." (PMID 34977873, 2021). "Genetic alterations of c-MET and EGFR were previously identified and implicated in the progression of several cancers and were also implicated in the resistance of most cancers to any generation of EGFR-TKIs including the latest third-generation series." (PMID 34512327, 2021). "The OncomineTM Pan-Cancer Cell-free NGS assay is designed to detect 982 hotspots in comparison to the targeted approach for the reference ddPCR test which interrogates specific EGFR, KRAS and BRAF mutations." (PMID 33494470, 2021). "It was noticed that cells with certain EGFR gene mutations and different levels of EGFR in cancer cells may make the cells differently sensitive to low or high LET radiation because radiation differentially affects tumors and healthy cells." (PMID 34094980, 2021). "The EREG/EGFR pathway may be a potential target and may be combined with other driver mutation targets to combat specific cancers." (PMID 34884633, 2021). "Therefore, various materials can inhibit skin inflammation or cancer by reducing factors linked to EGFR activation." (PMID 34943012, 2021). "In this review, we concluded a series of the published studies that focused on ARID1A in cancers and proposed the underlying mechanisms related to the resistance to EGFR-TKIs induced by ARID1A alterations or expression loss and the potential therapeutic strategies to overcome the resistance." (PMID 34715776, 2021). "Finally, NSCLC patients, with other driver gene changes or EGFR uncommon mutations, or patients of other kinds of cancer with gene mutations also have the problem of “optimal treatment,” which needs to be further studied by clinical workers and researchers." (PMID 34938345, 2021). "The second most important node in the context of association with Cancer is EGFR." (PMID 34200663, 2021). "It is well known that EGFR mutations can influence the prognosis of cancer." (PMID 33281971, 2021). "Liquid biopsy test reported actionable alterations in ARID1A gene, rearranged during transfection (RET) gene fusions, epidermal growth factor receptor (EGFR) gene R776H mutation, breast cancer (BRCA) genes 1/2, and cyclin-dependent kinase inhibitor 2A (CDKN2A) gene mutations." (PMID 33608032, 2021). "As a result, we speculate that the EGFR mutation is mixed with the individual’s whole genome and can be influenced by other cancer-related genes as well as its polymorphisms whether congenitally or progressively during lifetime." (PMID 33799753, 2021). "The phosphoproteins measured include extensively annotated functional sites on kinases and transcription factors belonging to key signaling pathways implicated in cancers, including Akt signaling, EGFR signaling, the RAS-RAF pathway, and hippo-signaling pathways." (PMID 34010657, 2021).
cancer (continued). "Thus, to develop new efficient therapeutic drugs, improvements for suppressing NSCLC cells of mutated EGFR are crucial in attenuating growth of malignant tumors." (PMID 35582384, 2021). "Notably, mutations in KEAP1/NFE2L2 and those in EGFR exclude each other in all cancer types with high somatic mutation rates in these genes, speaking for a high functional overlap of both pathways." (PMID 33916908, 2021). "Emphasizing on the potential role of Nf1 loss in resistance to BRAF and EGFR inhibitors, they also suggested this could be a potential strategy for other cancer types with related changes to the NF1-FAK1 pathway." (PMID 34781949, 2021). "It is used to treat patients suffering from cancer due to EGFR mutations." (PMID 34439865, 2021). "However, some mutations are cancer type specific such as EGFR vI (amino-terminal deletion), EGFR vII (deletion of exons 14–15), EGFR vIII (deletion of exons 2–7)." (PMID 34582442, 2021). "These processes promote cancer growth, and in some cases, they may cause cells to develop resistance to certain types of treatment, notably EGFR inhibitors." (PMID 34063682, 2021). "It is worth underlining that in cancer cells, ROS can also play the role of secondary messenger to activate multiple intracellular proteins and enzymes, including the epidermal growth factor receptor, c-Src, p38 mitogen-activated protein kinase, Ras and Akt/protein kinase B." (PMID 33924068, 2021). "Interestingly EGFR, belonging to the ErbB family of RTKs,21 has been demonstrated a known hallmark for multiple human carcinomas." (PMID 33960631, 2021). "Several studies have shown that the EGFR status is associated with drug resistance in cancer." (PMID 32413049, 2020). "EGFR has been demonstrated to be associated with cancer stem cell traits in HNSCC." (PMID 31823521, 2020). "Besides CD73 expression was induced by epidermal growth factor (EGF), and the pharmacological inhibition through EGFR-TKi induced its decrease in EGFR-mutated cancer cell lines." (PMID 32760402, 2020). "Comparison of TKI sensitivity among these cell lines showed that EGFR/KRAS co-mutated cells were more sensitive than parent cells, indicating that EGFR-TKIs may represent a treatment option for cancers harboring EGFR/KRAS co-mutation." (PMID 32130260, 2020). "Similar to the cases of the anti-HER2 ADCs, the development of the anti-EGFR ADC suggests that the technical hurdles associated with ADC targets may be overcome by taking advantage of the target biology in the context of cancer cells." (PMID 32111076, 2020). "(Calithera; Society for Immunotherapy of Cancer Meeting) A trial of CB-839 in combination with the third-generation epidermal growth factor receptor (EGFR) inhibitor osimertinib in EGFR-mutated NSCLC is also currently enrolling (ClinicalTrials.gov NCT03831932)." (PMID 32266129, 2020). "Indeed, the mutant Cbl-c binds to the EGFR and prevents the recruitment of the wild-type Cbl protein, suggesting that loss of Cbl-c is involved in cancer progression in solid tumors, both in mice and human models." (PMID 33114139, 2020). "This variation suggests that some individuals may be exposed to a greater susceptibility to the cancer-linked EGFR exon 19 canonical deletion." (PMID 31940362, 2020). "Furthermore, TR-PINs would potentially be effective in a broader range of PDAC and HNSCC patients, in addition to patients with various other cancer indications where EGFR, HER-2, and TfR over-expression are implicated." (PMID 32726945, 2020). "AGR2 was also required for delivery of EGFR to the plasma membrane that may contribute to oncogenic function in cancers since AGR2-deficient cells showed immature and cytoplasmic staining of EGFR." (PMID 33005802, 2020). "For cancer of unknown primary, EGFR mutation and ALK fusion were highly enriched in our cohort, which indicate that those tumors might originate from lung." (PMID 32373528, 2020).